EPAS1 (endothelial PAS domain protein 1)
Description:
Transcription factor involved in the induction of oxygen regulated genes. Heterodimerizes with ARNT; heterodimer binds to core DNA sequence 5'-TACGTG-3' within the hypoxia response element (HRE) of target gene promoters (By similarity). Regulates the vascular endothelial growth factor (VEGF) expression and seems to be implicated in the development of blood vessels and the tubular system of lung. May also play a role in the formation of the endothelium that gives rise to the blood brain barrier. Potent activator of the Tie-2 tyrosine kinase expression. Activation requires recruitment of transcriptional coactivators such as CREBBP and probably EP300. Interaction with redox regulatory protein APEX1 seems to activate CTAD (By similarity).
Synonyms: bHLHe73; HLF; HIF2A; MOP2; PASD2; ECYT4
Tractability: Small molecule: an approved drug acts on it; a structure with a bound ligand is known; a high-quality ligand is known; it has a binding pocket of medium quality; it belongs to a druggable protein family. PROTAC: UniProt records ubiquitination sites on it; ubiquitination databases record sites on it; a small molecule that binds it is known.
Target class: Transcription factor
Chemical probes: PT-2385 (high quality), PT2399 (high quality), TC-S 7009, TOPOTECAN
Safety:
Unwanted effects reported when the protein is acted on. In parentheses: how it was acted on, where the effect was seen, and who reports it.
dermatologic toxicity (source: ClinPGx)
drug toxicity (source: ClinPGx)
Gene: Protein-coding gene on chromosome 2 (46,293,667 to 46,386,697, forward strand). Ensembl gene ENSG00000116016.
Subcellular location: Nucleus; Nucleus speckle
Subcellular location (Human Protein Atlas): Nucleoplasm; Actin filaments; Cytokinetic bridge; Cytosol
Pathways (Reactome):
Cellular responses to stimuli: Cellular response to hypoxia; Oxygen-dependent proline hydroxylation of Hypoxia-inducible Factor Alpha; Regulation of gene expression by Hypoxia-inducible Factor
Autophagy: Pexophagy
Developmental Biology: Transcriptional regulation of pluripotent stem cells
Immune System: Regulation of PD-L1(CD274) transcription
Metabolism of proteins: Neddylation
Signal Transduction: PTK6 Expression
Gene Ontology:
Molecular function: protein binding; protein heterodimerization activity; RNA polymerase II-specific DNA-binding transcription factor binding; sequence-specific DNA binding; transcription coactivator binding; DNA-binding transcription factor activity, RNA polymerase II-specific; RNA polymerase II transcription regulatory region sequence-specific DNA binding; cis-regulatory region sequence-specific DNA binding; DNA binding; DNA-binding transcription activator activity, RNA polymerase II-specific; DNA-binding transcription factor activity; protein dimerization activity; RNA polymerase II cis-regulatory region sequence-specific DNA binding
Biological process: cellular response to hypoxia; positive regulation of transcription by RNA polymerase II; regulation of protein neddylation; response to hypoxia; angiogenesis; blood vessel remodeling; erythrocyte differentiation; intracellular oxygen homeostasis; lung development; myoblast fate commitment; positive regulation of cold-induced thermogenesis; regulation of transcription by RNA polymerase II; signal transduction; regulation of DNA-templated transcription
Cellular component: nucleoplasm; RNA polymerase II transcription regulator complex; transcription regulator complex; chromatin; cytosol; nuclear speck; nucleus; cytoplasm
Genetic constraint (gnomAD): Loss-of-function variants: 23 observed, 88.97 expected, observed/expected ratio (o/e) 0.26, 90% interval 0.19 to 0.37. The upper end of that interval is the gene's LOEUF score, 0.37, which puts it in group 1 of 6, group 1 being the genes least tolerant of losing a copy. Missense variants: 1,138 observed, 1,158.6 expected, observed/expected ratio (o/e) 0.98, 90% interval 0.94 to 1.03. Synonymous variants: 508 observed, 463.67 expected, observed/expected ratio (o/e) 1.1, 90% interval 1.02 to 1.18.
Cancer hallmarks: suppression of growth (promotes); tumour promoting inflammation (promotes); angiogenesis (promotes); escaping programmed cell death (promotes); invasion and metastasis (promotes); proliferative signalling (promotes)
Homologues: Orthologues: chimpanzee EPAS1 (99% identical), macaque EPAS1 (98% identical), pig EPAS1 (90% identical), mouse Epas1 (88% identical), rabbit EPAS1 (87% identical), rat Epas1 (85% identical), guinea pig EPAS1 (82% identical), dog EPAS1 (81% identical), tropical clawed frog epas1 (64% identical), zebrafish epas1b (56% identical), zebrafish epas1a (54% identical), Drosophila melanogaster sima (30% identical), and 2 more. Paralogues in human: HIF1A (44% identical), HIF3A (29% identical), NPAS3 (22% identical), SIM1 (19% identical), SIM2 (18% identical), NPAS1 (16% identical), NPAS4 (15% identical).
Diseases named in the same sentence as EPAS1 in open-access papers:
EPAS1 is named in the same sentence as 413 diseases in open-access papers, as found by Europe PMC text mining. Sharing a sentence is not in itself a finding about the gene and the disease. The quoted sentences say what the papers report.
breast carcinoma (190 papers, 2007 to 2026). "Among these, EPAS1 is associated with paclitaxel-resistant breast cancer, and KRT80 was recently reported to have an association with endocrine-resistant ERα breast cancer." (PMID 41007650, 2025). "We then demonstrated that HIF-2α (encoded by EPAS1) was directly regulated by SIPA1 in breast cancer cells." (PMID 35096814, 2021). "Estrogen receptor α was shown to function as a transcriptional repressor of EPAS1 in breast cancer cells and might be involved in sexual dimorphism of susceptibility toward EPAS1 PVs." (PMID 38481600, 2024). "Additionally, the expression of HIF-2α (EPAS1) is associated with ZEB2-induced EMT in breast cancer." (PMID 29164272, 2018). "In breast cancer, miR-152 inhibits cell survival and promotes apoptosis by targeting EPAS1, enhancing the sensitivity of breast cancer cells to paclitaxel." (PMID 39606232, 2024). "Chromatin accessibility of EPAS1 was increased in surviving breast cancer cells (HCC1806) at 10 DPT." (PMID 38385626, 2024). "For example, the transcription activity of EPAS1 was controlled by methylated CpG binding protein 3 in breast cancer, which ultimately modulated cellular responses to EPAS1." (PMID 36313570, 2022). "It has been reported that EPAS1 is expressed abnormally in several tumors, including breast cancer, and has a large effect on the regulation of metastasis and progression of breast cancers 36,37." (PMID 32913475, 2020). "EPAS1, on the other hand, is relatively well studied in its relation to cancer, including breast cancer." (PMID 33218035, 2020). "In breast cancer, the role and expression levels of EPAS1 have been indicated to be subtype specific." (PMID 33218035, 2020). "As detected by qRT-PCR, the expression of EPAS1 in normal tissues was remarkably lower than in breast cancer tissues, which contrasted the expression pattern of miR-152-3p." (PMID 32913475, 2020). "Conclusion: miR-152-3p inhibits the survival of MCF-7/TAX cells and promotes their apoptosis by targeting the expression of EPAS1, thereby, enhancing the sensitivity of these breast cancer cells to paclitaxel." (PMID 32913475, 2020). "The relationship between EPAS1 and miR-152-3p and their roles in paclitaxel resistance of breast cancer were further investigated using RNA interference and transfection techniques." (PMID 32913475, 2020). "It was noted that the suppression of EPAS1 via shRNA in breast carcinomas cells reduced the cellular response and inhibited angiogenesis significantly, resulting in reduced tumour growth and development." (PMID 33114456, 2020). "For instance, EPAS1 could enhance the effect of paclitaxel on breast cancer cells by inhibiting growth and promoting apoptosis of MCF-7/TAX cells." (PMID 34901000, 2021). "In addition, shRNA‐mediated silencing of EPAS1 inhibited the cellular response and halt angiogenesis in breast cancer significantly." (PMID 34250767, 2021). "Furthermore, suppression of EPAS1 using shRNA in breast carcinoma cells reduced the cellular growth and inhibited angiogenesis." (PMID 33042797, 2020). "In the present study, we examined the role of miR-152-3p in the development of paclitaxel resistance in breast cancer, and further explored whether targeting of EPAS1 by this miRNA is involved in such resistance." (PMID 32913475, 2020). "This suggests that EPAS1 is related to paclitaxel resistance in breast cancer cells." (PMID 32913475, 2020). "In previous studies, our research group confirmed that the abnormal expression of endothelial PAS domain-containing protein 1 (EPAS1) is related to the proliferation, invasion, and angiogenesis of breast cancer, and participates in the chemoresistance of this cancer." (PMID 32913475, 2020). "Finally, we selected 245 cases CD44+CD24− (breast cancer stem cells phenotype marker) breast cancer patients from TCGA dataset to analyze correlation of EPAS1 with Wnt and Notch pathways related factors, and c-Myc." (PMID 30340507, 2018).
breast carcinoma (continued). "To further decipher the relationship between miR-152-3p and EPAS1 and their effects on the progression of breast cancer, we used qRT-PCR, Spearman's correlation, and western blot analyses to show that miR-152-3p may play a negative regulatory role in the expression of EPAS1." (PMID 32913475, 2020). "We used RT-qPCR to determine RG candidate levels in normoxic breast cancer cells, removing TBP and EPAS1 from downstream analysis due to insufficient transcript abundance." (PMID 39838295, 2025). "This study’s findings place UC within a particular group of cancers, including renal cell carcinoma, HER2-positive breast cancer, hepatocellular carcinoma, and head and neck cancers, in which HIF-2/EPAS1 expression has prognostic value." (PMID 36421334, 2022). "In breast cancer, eight winning TFs (ZBTB16, KLF2, KLF4, NR2F1, EGR1, FOSB, EPAS1, and GPRASP1) can form a coregulatory network, and three other winning TFs (MYBL2, FOXM1, and TAL1) can form another coregulatory network." (PMID 36101460, 2022). "The mRNA levels of EPAS1 as well as TGFB1, VEGFA and CA9, were confirmed to be positively correlated with those of SIPA1 in these two pairs of breast cancer cells and BT549, another TNBC cell line." (PMID 35096814, 2021). "It is thus likely that SIPA1 directly interacted with the EPAS1 promoter, enhanced its promoter activity and promoted HIF-2α expression in breast cancer cells." (PMID 35096814, 2021). "We determined that the basal breast cancer cell lines (BT20, MDA-MB231, MDA-MB157) had consistently higher mRNA levels of both HIF1A (HIF-1α) and EPAS1 (HIF-2α) when compared to the luminal cell lines (MCF7, BT474, CAMA1)." (PMID 21672245, 2011). "Moreover, high expression of EPAS1/HIF2α, AREG and WISP2 is linked to improved survival in breast cancer; glyceollin treatment does not affect EPAS1/HIF2α expression in the absence of E2 treatment and even partially restores expression in E2-treated cells." (PMID 28666461, 2017). "Consistent with our findings in the basal-breast cancer cell line, AU565 cells (subgroup 7) demonstrated that silencing of HIF1A (HIF-1α), but not EPAS1 (HIF-2α), led to the abolishment of the exaggerated hypoxia response seen in these cells." (PMID 21672245, 2011).
renal cell carcinoma (137 papers, 2005 to 2026). "On the other hand, MCP-induced protein 1 has been reported to negatively regulate EPAS1 transcription by acting as a regulator of stability and half-life of transcript encoding HIF2α in human renal cell carcinoma cell line." (PMID 34209205, 2021). "This is consistent with multiple pieces of evidence from the literature, which suggest a causal role of EPAS1 in renal cell carcinoma." (PMID 34828399, 2021). "Dysregulation of EPAS1 is associated with the carcinogenesis of different types of cancers such as lung carcinoma, renal cell carcinoma, hepatocellular carcinoma, neuroblastoma, pheochromocytoma, glioma, and colorectal adenocarcinoma." (PMID 33042797, 2020). "In keeping with this, EPAS1 (encoding HIF-2α) polymorphisms have been identified as one of the two susceptibility loci in renal cell carcinoma." (PMID 25893706, 2015). "Accordingly, it was reported that expression of EPAS1 is associated with pathogenesis, progression, and prognosis of different cancers, including non–small cell lung carcinoma, renal cell carcinoma, hepatocellular carcinoma, neuroblastoma, pheochromocytoma, glioma, and colorectal carcinoma." (PMID 33042797, 2020). "Tumor-promoting oncogenic roles of EPAS1 was noted in the pathogenesis of lung carcinoma, renal cell carcinoma, liver neuroblastoma, pheochromocytoma, and so on, whereas other studies reported the tumor-suppressive properties in the pathogenesis of glioma, colorectal carcinoma, and neuroblastoma." (PMID 33042797, 2020). "In renal cell carcinoma (RCC), hypoxia induces EPAS1 activation and up-regulates the expression of HILPDA to promote PUFAs production and subsequent lipid peroxidation, and induce ferroptosis." (PMID 34996454, 2022). "As for the regulated targets in the renal cell carcinoma pathway, TGFB1, EPAS1, HIF1A, VEGFA, KRAS, and PIK3CA regulated by miR-140 have been reported to interfere with KIRC." (PMID 35528546, 2022). "For example, in von Hippel-Lindau-defective renal cell carcinoma (RCC), HIF-1α inhibits cell proliferation in vivo or in vitro, and the knockdown of HIF-1α promotes tumor growth accordingly, while EPAS1 is shown to be essential for the growth of xenograft in RCC." (PMID 37124944, 2023). "Furthermore, HIF-2 (EPAS1) has been shown to promote hypoxia response element (HRE)-driven gene expression, and shRNA knockdown increased renal cell carcinoma sensitivity to ionizing radiation." (PMID 22829886, 2012).
clear cell renal cell carcinoma (128 papers, 2010 to 2026). "Increased erythropoietin (EPO) in patients with familial/idiopathic erythrocytosis and pulmonary hypertension is associated with mutations in EGLN1 (PHD2) and EPAS1 (HIF2α); a drug inhibiting HIF2α activity is used for clear cell renal cell carcinoma (ccRCC) treatment." (PMID 37449559, 2023). "We use genetic, epigenetic and transcriptomic data from large patient cohorts and cell models to dissect mechanisms of augmented EPAS1 transcription in clear cell renal cell carcinoma." (PMID 41714613, 2026). "Roles of EPAS1 in cancer pathogenesis have been reported in several malignancies such as pancreatic, breast and clear cell renal cell carcinomas." (PMID 34250767, 2021). "Accordingly, silencing of endothelial PAS domain protein 1 (EPAS1; best known as HIF2A) in clear cell renal cell carcinoma or HIF1A in melanoma and prostate cells reduced PD-L1 expression and restored cytotoxic T lymphocyte (CTL)-mediated tumor cell killing in vitro." (PMID 31535086, 2019).
glioma (108 papers, 2007 to 2025). A benign or malignant brain and spinal cord tumor that arises from glial cells (astrocytes, oligodendrocytes, ependymal cells). "In contrast, the expression levels of the hyaluronic acid receptor Cd44 and the gene encoding hypoxia-inducible factor 2 alpha (HIF2a), Epas1, were lower in rat glioma 101.8 relative to healthy brain tissue." (PMID 41009560, 2025). "Epas1 expression is correlated with the expression of another important marker of glioma stem cells (GSCs), the hyaluronic acid receptor gene Cd44." (PMID 41009560, 2025). "Apparently, there was a high amount of stabilized HIF-2a in rat glioma 101.8 tumor cells, which led to a decrease in Epas1’s mRNA expression level via a negative feedback mechanism." (PMID 41009560, 2025). "SPP1 acts as a CD44 ligand in glioma, promoting the production of the oncogene EPAS-1 and aggresive glioma development." (PMID 36059672, 2022). "EPAS1/HIF2A has been proposed as a CSC marker not only in melanoma but also in other cancers like glioma." (PMID 24098529, 2013). "However, high vascularization was observed in rat gliomas 101.8, which might lead to decreased expression of Epas1 and Cd44." (PMID 41009560, 2025). "Out of these NRGs, 19 NRGs (EGLN3, HILPDA, HMBS, HYOU1, BNIP3, etc.)were found to be enriched in glioma tissues while 13 genes (SLC4A1, IL6, EPAS1, ACE, HMOX1, etc.)were decreased compared to normal tissues." (PMID 37934582, 2023). "In contrast, in glioma stem cells, one of the human HIF−1 homologs, HIF-2α/EPAS1, is inhibited by DYRK1A/B in a VHL-dependent manner." (PMID 28562327, 2017).
renal carcinoma (99 papers, 2007 to 2026). A carcinoma arising from the epithelium of the renal parenchyma or the renal pelvis. "Although genetic polymorphisms link the EPAS1 oncogene (coding for HIF-2α) to renal cancer and anti-HIF-2 compounds emerge as renal tumor therapies, little is known about transcriptional dysregulation of this factor in renal malignancies." (PMID 41714613, 2026). "Previous evidence demonstrated that restoration of wild type VHL in human renal cancer cells decreased their NK susceptibility while VHL mutations increased resistance to NK-mediated lysis through EPAS1/HIF-2α stabilization." (PMID 30514329, 2018). "That many of the currently known renal cancer-associated SNPs (EPAS1, CCND1 and MYC/PVT1) can be linked to modulation of a single pathway (that is, the HIF pathway) is striking and to our knowledge unique in tumour biology." (PMID 27774982, 2016). "OSRC2 and TUHR4TKB renal carcinoma cell lines are examples of pVHL-defective ccRCC lines that display a proliferative disadvantage after CRISPR-mediated inactivation of EPAS1 in competition assays carried out over weeks in vitro." (PMID 40178040, 2025). "ITPR1 serves as a direct target of EPAS1 and an autophagy regulator to protect renal carcinoma cells against NK-mediated killing." (PMID 34621314, 2021). "In the Human Protein Atlas, the EPAS1 mRNA was detected in various cancer tissues and EPAS1 is used as a prognostic marker in renal cancer." (PMID 34828399, 2021). "In the Human protein atlas EPAS1 mRNA was reported in 15 different cancer types, with the highest expression and as a prognostic marker in renal carcinoma." (PMID 34828399, 2021). "EPAS1 also called hypoxia-inducible factor-2α (HIF-2α), has been reported to play an oncogenic role in various cancers including gastric cancer, colon cancer, lung cancer, pancreatic cancer, renal cancer, etc24–28." (PMID 30696880, 2019). "In renal cancer EPAS1 plays an important role in resistance to chemotherapeutics." (PMID 24098529, 2013). "We define an oncogenic enhancer of EPAS1 which operates depending on the presence of HIF and renal lineage-specific factors, thereby providing evidence for an auto-regulatory feed-forward circuit of HIF-2α regulation which promotes renal cancer growth." (PMID 41714613, 2026).